TNF (tumor necrosis factor)
Diseases named in the same sentence as TNF in open-access papers (continued):
Sharing a sentence is not in itself a finding about the gene and the disease.
acute respiratory distress syndrome (continued). "Similarly, in a mouse model of acute respiratory distress syndrome (ARDS), treatment with THC led to a 100% survival rate, a reduction in the infiltration of immune cells into the lungs, and a reduction in the proinflammatory cytokines IFN-γ, IL-1β, IL-2, IL-6, and TNF-α." (PMID 38202234, 2023). "The increased vascular permeability and pulmonary edema are prominent features of ALI and acute respiratory distress syndrome (ARDS), which are commonly assumed to relate to the levels of critical soluble cytokines, such as vascular endothelial growth factor (VEGF) and TNFα." (PMID 35336858, 2022). "More particular markers, such as interleukin-6, interleukin-1, and TNF-α, play an important role in disease severity, especially in patients with acute respiratory distress syndrome (ARDS), but they are more expensive and not readily available for routine clinical use." (PMID 40428888, 2025). "For example, low IL‐10/TNF‐α ratios, rather than absolute plasma TNF‐α or IL‐10 concentrations, best correlated with adverse outcomes in patients with acute respiratory distress syndrome (ARDS)." (PMID 32940965, 2020).
preeclampsia (249 papers, 2005 to 2026). Preeclampsia is a hypertensive disorder of pregnancy that is characterized by new-onset hypertension with proteinuria presenting after 20 weeks of gestation, and depending on mild or severe forms may initially present with severe headache, visual disturbances, and hyperreflexia. "The elevated level of TNF-α is highly related to pregnancy loss and preeclampsia and contributes to abnormal production of cytokines and chemokines in syncytiotrophoblasts." (PMID 40979093, 2025). "As early as 2011, a meta-analysis sought to investigate the role of the inflammatory factors TNF-a, IL-6, and IL-10, assessing both their serum expression levels and the presence of polymorphisms in women with preeclampsia." (PMID 38893732, 2024). "TNF-α increases during all pregnancy and has been related to miscarriages, fetal losses, preeclampsia, and preterm birth and is associated with IL-10 reduction." (PMID 37887854, 2023). "Preeclampsia is associated with significantly higher levels of the proinflammatory cytokine TNF-α than uncomplicated pregnancies." (PMID 37887854, 2023). "As others have found, we were not able to detect many other proinflammatory cytokines associated with preeclampsia, such as resistin or TNFα." (PMID 35329840, 2022). "A study demonstrated that certain pathological pregnancies, such as recurrent abortion, premature delivery and severe preeclampsia, as well as recurrent implantation failure syndrome, are closely associated with elevated Th1 cytokines, especially TNF-α." (PMID 36303229, 2022). "It was also shown that increased levels of TNF-α are associated with pregnancy loss and preeclampsia." (PMID 33805757, 2021). "They found that the EPA diet significantly lowered the plasma concentrations of the inflammatory factors interleukin-6 and tumor necrosis factor α, which can influence placental development and increase the risk of developing preeclampsia." (PMID 33603029, 2021). "Novel evidence confirms that high levels of TNF-α have been associated with an increased risk of preeclampsia." (PMID 34906255, 2021). "In a prospective cohort study the frequency of TNF-α -308G > A variant was investigated in 1652 pregnant women with intrauterine fetal death, preeclampsia, preterm labor before 34 gestational weeks, and small-for-gestational-age (SGA) infants." (PMID 33838693, 2021). "Many proinflammatory markers have been implicated in preeclampsia including IL-6, IL-8, IL-10, IL-17, and TNF-α." (PMID 34780565, 2021). "There was normal ZO-1 immunostaining in untreated or HUVECs treated with sera from normal pregnancies, with the loss of immunostaining in cells treated with either TNF-α or preeclampsia sera." (PMID 32260307, 2020). "We analyzed a panel of genes which are triggered by inflammation and are known to be associated with TNF-induced apoptosis and preeclampsia." (PMID 31991780, 2020). "MPO has been associated with hypertension, and elevation in TNF-α is recognized as a driving inflammatory mechanisms to preeclampsia." (PMID 33013837, 2020). "In a rat model, TNF-α is causally linked to deficient trophoblast invasion and spiral artery remodeling, leading to features of preeclampsia and FGR." (PMID 30448406, 2019). "For example, infection with Chlamydia trachomatis increases levels of IFN-γ in cervical secretions, the secretion of IL-1β and TNF-α in dendritic cells, and the risk of preeclampsia." (PMID 30448406, 2019). "Increased TNF-α is associated with a number of adverse pregnancy conditions including gestational hypertension and gestational diabetes mellitus (GDM)." (PMID 28097431, 2017). "For instance, recently, preeclampsia was associated to gene variants present in the upstream regulator of TNFα in European Americans28." (PMID 26758611, 2016).
preeclampsia (continued). "Studies have shown high IL-1β and TNF-α concentration in serum or amniotic fluid are associated with adverse pregnancy outcomes, including first-trimester losses, preeclampsia and gestational diabetes mellitus, and preterm birth." (PMID 27978823, 2016). "The antibody titer in cases of severe preeclampsia was associated with the grade of retinopathy, and positively correlated with the level of TNF-α and VEGF." (PMID 27381670, 2016). "Genetic polymorphisms of TNF-α and IL-1 result in increased levels of these pro-inflammatory cytokines and are associated with preeclampsia." (PMID 26247971, 2015). "Taking into account the inheritable nature of preeclampsia there has been widespread research for identifying any association between a number of genes and the risk for developing preeclampsia, and TNF-α has been a part of these investigations." (PMID 24719701, 2014). "This study was designed to evaluate the role of TNF-α polymorphism at position -238 in the risk of developing preeclampsia during pregnancy." (PMID 24719701, 2014). "In this study, we found an association between polymorphisms at -238 TNF-α and the risk of developing preeclampsia in the Iranian population." (PMID 24719701, 2014). "Recently, it was reported that recombinant interleukin-6 (IL-6) and TNFα were capable of activating endothelial cells, which is a hallmark of preeclampsia." (PMID 24060241, 2013). "Maternal circulating proinflammatory cytokines (IL-1β, TNFα) induced by infection or inflammation have previously been associated with preeclampsia." (PMID 20940111, 2011). "The fact that higher circulating levels of TNF-alpha were observed in preeclampsia than in gestational hypertension suggests an association with disease severity." (PMID 21253506, 2010). "Preeclampsia is associated with an exacerbated inflammatory response that may lead to a release of pro-inflammatory cytokines, including TNF-α, interleukin-6 (IL-6), interleukin-8 (IL-8), and interleukin-1 beta (IL-1β)." (PMID 40109359, 2025). "There is emerging evidence that FGR and preeclampsia share common pathways, with a pro-inflammatory bias of increased levels of IL-6, IL-8 and TNF-α; however, FGR has been associated with decreased levels of the anti-inflammatory cytokine IL-10 in peripheral blood." (PMID 39124698, 2024). "Furthermore, cytokines secreted by the M2b phenotype, including TNF‐α, IL‐1β, and IL‐6 have been associated with preeclampsia." (PMID 37269190, 2023). "The results indicate that TNF-α-308G/A gene polymorphism may play important roles in the pathogenesis of severe preeclampsia." (PMID 36979841, 2023). "As a state of chronic inflammation, overweight will increase the risk of preeclampsia by means of activating macrophages, NK cells, and peripheral helper T cells within the placenta to produce inflammatory cytokines such as IL-6, IL-7, and TNF-α." (PMID 36833689, 2023). "Elevated TNF-α is associated with recurrent pregnancy loss, early and severe preeclampsia, and recurrent implantation failure; all of these are “idiopathic” or related to antiphospholipid positivity, which implies the important role of TNF-α in maintaining normal pregnancy." (PMID 35600817, 2022). "Interestingly, PPARγ has a critical role in regulating inflammatory cytokines including TNF-α and IL-6, which were linked to preterm labor, miscarriage, and preeclampsia." (PMID 35011648, 2021). "Hydroxychloroquine rescued the loss of ZO-1 induced by both TNF-α and preeclampsia sera." (PMID 32260307, 2020). "At the same time, TNF might be detrimental to pregnancy, causing complications such as miscarriage and preeclampsia." (PMID 30986974, 2019). "In addition, since development of preeclampsia was reported to be caused by defective trophoblastic invasion, probably through increased pro-inflammatory cytokine TNF-α and decreased anti-inflammatory IL-10." (PMID 29225576, 2017).
preeclampsia (continued). "Several studies have looked for an association between preeclampsia and different single nucleotide polymorphisms in the promoter region of TNF-α gene which could affect its expression." (PMID 24719701, 2014). "Interestingly, infusion of TNF-α or IL-6 in pregnant rats to reach plasma levels similar to those observed in preeclampsia, are associated with inceassed BP and systemic vasoconstriction." (PMID 23580870, 2013). "It is also associated with inflammatory mechanisms related to implantation, placentation, and pregnancy outcome, since over-production of TNF-α may lead to such events as recurrent pregnancy loss, early and severe preeclampsia, and recurrent implantation failure syndrome." (PMID 36355514, 2022). "The current view on preeclampsia suggests that preeclampsia has an exaggerated maternal systemic immune response component, and indeed, blood-group antigens influence the bioavailability of E-selectin, TNF-alpha and ICAM1, factors implicated in the pathogenesis of preeclampsia." (PMID 21799738, 2011). "Preeclampsia is characterized by systemic endothelial dysfunction, upregulation of inflammatory cytokines (e.g., IL-6, TNF-α), oxidative stress, and alterations in cerebral microvascular perfusion." (PMID 41517645, 2026). "Key terms included variations of “preeclampsia,” “pre-eclampsia,” “gestational hypertension,” and “toxemia” for the condition, alongside terms like “inflammation,” “inflammatory markers,” “cytokines,” “interleukins,” “TNF-alpha,” and “CRP” for the biomarkers." (PMID 40786291, 2025). "The nonparametric Kruskal–Wallis test was used to assess differences in the level of the CD56+TNF+ subpopulation between the three clinical groups (control, gestational hypertension, preeclampsia)." (PMID 41463130, 2025). "Women with preeclampsia were found to exhibit increased concentrations of interleukin (IL)-1, IL-6, and tumor necrosis factor alpha (TNF-α) in their plasma and amniotic fluid, alongside elevated levels of IL-2 and interferon gamma (IFN-γ)." (PMID 41375625, 2025). "STB stress plays a central role in the pathogenesis of preeclampsia, suggesting that our model of TNF-α-induced stress in bioprinted trophoblast organoids resembles a preeclamptic placenta." (PMID 40940337, 2025). "Inflammation and systemic immune response: Periodontal infections induce chronic systemic inflammation, increasing the production of pro-inflammatory cytokines (IL-6 and TNF-α) and CRP, which are also implicated in preeclampsia." (PMID 40496368, 2025). "A recent comprehensive review indicates that most studies found women with preeclampsia exhibit elevated blood levels of cytokines (IL-6, IL-8, TNF-α, and C-reactive protein) compared to normotensive pregnant women." (PMID 41375625, 2025). "Studies show that TNF-α is a key pro-inflammatory cytokine that plays a central role in the pathogenesis of preeclampsia." (PMID 41463130, 2025). "Bioprinted organoids were used for a drug screening with aspirin (0.5 mM) or metformin (0.5 mM) to investigate their ability to ameliorate inflammation-induced (TNFα 20 ng/ml) trophoblast dysfunction in the context of preeclampsia." (PMID 40940337, 2025). "After FMT in mice treated with antibiotics, we found that the levels of serum LPS, IL-6, and TNF-α in the group of mice transplanted with fecal microbiota fluid from patients with preeclampsia were higher than those in the other three groups." (PMID 40832058, 2025). "TNF-α is a key proinflammatory cytokine involved in preeclampsia pathogenesis, and its effects on trophoblast cells are directly relevant to understanding the interplay between inflammation and oxidative stress in this condition." (PMID 40109359, 2025). "In preeclampsia, there is an increase in the level of pro-inflammatory cytokines such as TNF, IL-6, and IL-17, which contributes to the development of cytotoxic inflammation." (PMID 40647643, 2025).
preeclampsia (continued). "The overexpression of circulating IL-6, IL-8, IL-1β and tumour necrosis factor-alpha (TNF-α) in cases of preeclampsia maintain a chronic pro-inflammatory state." (PMID 39124698, 2024). "Subcutaneous adipose tissue staining revealed a heightened inflammatory response in preeclampsia, indicated by elevated levels of TNF-alpha and MCP-1 compared to normotensive pregnancies (p < 0.001 and 0.024, respectively)." (PMID 39125960, 2024). "This phenomenon resulted from higher cytokine concentrations (such as IL-12, TNF-α, and IL-1β) in early- versus late-onset preeclampsia." (PMID 38229046, 2024). "Findings from clinical studies have also associated changes in cord TNF-α and IFN-γ concentrations with poor fetal growth in the context of preeclampsia and pre-term birth." (PMID 38671859, 2024). "We developed this model to resemble a key feature of the preeclamptic placenta by including an important inflammatory factor, TNF-α, secreted by immune cells and shown to be increased in preeclampsia." (PMID 36652019, 2023). "During preeclampsia development, maternal inflammatory cytokines (IL‐Iβ, IL‐6, IL‐8 and TNFα) are activated, reducing the expression of eHsp‐27 and increasing the eHsp‐60 and eHsp‐70 levels." (PMID 37002651, 2023). "This study highlights elevated TNFα in maternal serum contributes to autism-like phenotypes in offspring exposed to preeclampsia and gives a therapeutic target to prevent it." (PMID 37290815, 2023). "The inflammatory cytokine IFN‐γ and TNF‐α generated by CD8+ T cells were significantly enhanced in pathological pregnancies including recurrent abortion or preeclampsia." (PMID 37771913, 2023). "In preeclampsia, TNF-α reaction was observed in degenerated decidua cells, in leukocytes and in villi." (PMID 37603530, 2023). "TNF-α and IL-6 increase gradually with the severity of preeclampsia from gestational hypertension to mild preeclampsia and severe preeclampsia." (PMID 37887854, 2023). "The preeclampsia group had the least placental damage (placental expression: caspase-3 [9.88±3.25], caspase-1 [4.21±3.16], and TNF-alpha [7.42±4.28])." (PMID 37362630, 2023). "Preeclampsia is a state of chronic inflammation with an immune imbalance where proinflammatory cytokines are increased (TNF-α, IL-6, IL-17) and anti-inflammatory cytokines are reduced (IL-10, IL-4)." (PMID 37887854, 2023). "BCL-3 regulates the expression of TNF-α to inhibit the innate immune response; however, the overexpression of BCL-3 is associated with early-onset preeclampsia." (PMID 37505866, 2023). "The study findings revealed that there was a statistically positive correlation between the serum levels of triglycerides, cholesterol, low-density lipoprotein, β-hCG, and TNF-α and the severity of preeclampsia." (PMID 37685488, 2023). "It is a known fact that elevated levels of TNF-alpha play a significant role in mediating inflammation in preeclampsia as well as APS." (PMID 37626793, 2023). "Preeclampsia is a pregnancy complication Aim of this study was to investigate expression of Beclin1 and tumor necrosis factor (TNF)-α in normotensive and preeclamptic placentas of pregnant women patients." (PMID 37603530, 2023). "The human placenta secretes TNF-α under hypoxia-reoxygenation conditions in vitro, mimicking the fluctuation of oxygen levels observed in preeclampsia." (PMID 36420416, 2022). "This study is designed to explore the effect of compound Danshen injection combined with magnesium sulfate on TNF-α, NO, oxidative stress, and therapeutic efficacy in severe preeclampsia (S-PE)." (PMID 35898773, 2022). "Preeclampsia also promoted TNF-α-, TGFβ1-, and VEGFA-induced proliferation of HUVEC from female offspring, but not in HUVEC from male offspring." (PMID 36420416, 2022). "In fact, the presence of high levels of TNF in maternal blood and amniotic fluid of patients with preeclampsia has been confirmed." (PMID 35165550, 2022).